RNU4-33P (RNA, U4 small nuclear 33, pseudogene)
Gene: Small nuclear RNA gene on chromosome 4 (119,367,562 to 119,367,646, forward strand). Ensembl gene ENSG00000201186.
Homologues: Orthologues: chimpanzee U4 (100% identical), macaque U4 (98% identical), dog U4 (82% identical), guinea pig U4 (76% identical), tropical clawed frog U4 (75% identical), tropical clawed frog U4 (73% identical), tropical clawed frog U4 (72% identical), tropical clawed frog U4 (71% identical), tropical clawed frog U4 (69% identical), tropical clawed frog U4 (67% identical). Paralogues in human: RNU4-87P (95% identical), RNU4-6P (82% identical), U4 (82% identical), RNU4-40P (81% identical), RNU4-91P (81% identical), U4 (81% identical), RNU4-15P (80% identical), RNU4-36P (80% identical), RNU4-42P (80% identical), RNU4-55P (80% identical), RNU4-79P (80% identical), RNU4-84P (80% identical), and 81 more.